CD4 (CD4 molecule)
Diseases named in the same sentence as CD4 in open-access papers (continued):
Sharing a sentence is not in itself a finding about the gene and the disease.
lymphopenia (continued). "Indeed, we recently reported naïve CD4+ lymphopenia and effector/memory T cell activation in older chronic HCV infected and HCV/HIV co-infected individuals, respectively." (PMID 35062255, 2021). "The release of chemokines such as CXCL-10/IP-10 and CCL-2/MCP-1 may also contribute to CD4 lymphopenia, mostly due to the suppression of hematopoietic progenitor cells proliferation, or to the inhibition of IL-2 signaling pathway." (PMID 34122423, 2021). "As in PR3-AAV, we confirmed the existence of lymphopenia, especially CD4+ T cells in MPO-AAV." (PMID 34289887, 2021). "All CGD patients with C. violaceum infection displayed CD4 + (T helper cells) lymphopenia." (PMID 34001231, 2021). "Our data showed that patients at higher risk of developing TB-IRIS exhibited more severe CD4+ T cell lymphopenia then those who did not." (PMID 34691079, 2021). "Both T- and B-cell lymphopenia and an inadequate repertoire of CD4+ and CD8+ T cells for at least 1 year after transplant increase the risk of recurrent reactivation of latent viruses, which may further contribute to a higher risk for development of aGvHD." (PMID 35087775, 2021). "Lymphopenia is typically profound after administration of alemtuzumab, reaching a nadir within a month of treatment, and lasts for three to 12 months for affected B-cells and up to three years for suppression of CD4+ and CD8+ cells." (PMID 33807678, 2021). "In the process of occurrence and development of acute myocardial infarction, the body is in a state of inflammatory activation, the level of blood cortisol increases, and the increased cortisol induces apoptosis, resulting in lymphopenia and CD4+/CD8+ T lymphocyte ratio inversion." (PMID 34075154, 2021). "Another consensus document proposed no discontinuation of prophylaxis until peripheral blood CD4+ T-cell count recovers to more than 200 cells/mL, as alemtuzumab-associated lymphopenia clinically behaves like that seen in patients with HIV infection." (PMID 33807678, 2021). "In addition, it has been demonstrated that in primary Sjögren’s syndrome (pSS), lymphopenia mainly occurred in naïve CD4+ T cells." (PMID 33923792, 2021). "Moreover, the lymphocytes in the “High-risk” group showed a systemic disorder, including TCR diversity decreasing and CD4 Tem amplification occurring, which was found in the state of lymphopenia in prior studies." (PMID 34993135, 2021). "Common features with our case include LBCL treated with axi‐cel to CMR, exposure to multiple prior lines of therapy (median 4, range 3–4; prior autologous stem cell transplantation (SCT) in Cases 1 and 2), persistent CD4+ lymphopenia (<200 cells/μl), and hypogammaglobulinaemia (<4 g/L)." (PMID 35845220, 2021). "A similar study (NCT00839436) in patients with idiopathic CD4+ lymphopenia also showed that rhIL-7 could increase the number of circulating CD4+ and CD8+ T cells." (PMID 34539637, 2021). "Naïve CD4+ lymphopenia and T cell activation are two key features of an ageing immune system." (PMID 35062255, 2021). "Here, we will provide insights into the recent literature showing that T cell death in the periphery and systemic immune activation may contribute to naïve CD4+ lymphopenia." (PMID 35062255, 2021). "She had lymphopenia and an inverted CD4/CD8 ratio before therapy." (PMID 33731004, 2021). "Moreover, in most HIV+/aTB+ patients with the most severe lymphopenia (CD4 frequency < 10%), SARS-CoV-2–specific responses were undetectable." (PMID 33945513, 2021). "Regarding the sustained high frequencies of cytotoxic CD8+ T cells detected in TB-IRIS patients; we hypothesize that this might be a compensatory mechanism for the elimination of mycobacterium-infected cells in the face of substantial CD4 lymphopenia." (PMID 34691079, 2021).
lymphopenia (continued). "Several other studies also linked abnormal immune functioning, such as elevated levels of cytokines, i.e., cytokine storm or hypercytokinemia, lymphopenia, and reduction in the proliferation of CD4+ T cells during SARS-CoV-2 infection with the hepatic injuries and severe liver damage in some cases." (PMID 34066983, 2021). "First, several severe patients showed increased Treg proportions among CD4+ T cells: for some as an increased proportion only (likely resulting from preferential resistance among CD4+ T cells during lymphopenia); for others, from true numerical increase relative to healthy donors (HD)." (PMID 34433692, 2021). "TNFSF10, induces apoptosis of CD4 + and CD8 + T cells and is upregulated, which might explain the cause of lymphopenia in the process of ASFV infection." (PMID 34412678, 2021). "Treg proliferation in vivo appears to be driven primarily by CD4 lymphopenia." (PMID 34526990, 2021). "Systemic lymphopenia, which in our population seems to affect primarily CD4+ T cells, could be the consequence of cell infiltration and sequestration in the lung." (PMID 34925369, 2021). "Importantly, their lymphopenia tended to improve over time; longitudinal analysis found that although CD8 + T cell lymphopenia persisted, CD4+ T cell lymphopenia became less severe past 2 years of age." (PMID 33987750, 2021). "Two key immunological signatures that were associated with chronic HCV infection (regardless of cirrhosis state), HIV infection, and ageing are naïve CD4+ lymphopenia and chronic systemic immune activation (elevated levels of soluble inflammatory and cellular activation markers)." (PMID 35062255, 2021). "This might be especially beneficial for older individuals who frequently have lower numbers of CD4 T cells, and for cancer patients with treatment-induced lymphopenia." (PMID 33923363, 2021). "Faced with a high clinical suspicion of CVID and marked CD4+ T lymphopenia, care must be taken when assessing these parameters that could be related to iatrogenesis." (PMID 34108596, 2021). "Over the next 15 years, there was evidence of progressive CD4+ T cell and B cell lymphopenia." (PMID 34908525, 2021). "Lymphopenia, which affects both CD4 and CD8 subsets, is a very frequent finding." (PMID 34315546, 2021). "In these experiments, CD4 T-cell priming boosted by lymphopenia (achieved via irradiation, cytotoxic drug treatment or immunodeficient host environment) supported CD4 T-cell differentiation into IFNγ-producing, cytolytic effector cells that infiltrated tumors and killed their targets directly." (PMID 34201655, 2021). "It leads to immunodeficiency and lymphopenia with a decrease in CD4+ T cells." (PMID 34926494, 2021). "Notably, compelling data suggest profound lymphopenia of naïve T cells in both the CD4+ and CD8+ compartments in ESRD, although the underlying mechanism is not sufficiently understood." (PMID 33815398, 2021). "Interestingly, we also found increased CD31-CD4+ T cells in sepsis, suggesting peripheral proliferation of naïve CD4+ T cells to substitute for T-cell depletion, a phenomenon known as lymphopenia-induced homeostatic proliferation (HP)." (PMID 32825352, 2020). "Furthermore, two additional primary immunodeficiencies that compromise T cell receptor signaling present with CD4+ T cell lymphopenia and uncontrolled EBV infection, as observed under FK506 treatment of EBV-infected humanized mice." (PMID 32251475, 2020). "Excessive inflammatory reactions may lead to immune disorders, including lymphopenia and a redistribution of CD4+ T cells." (PMID 32793529, 2020). "Clinical phenotype of eczema, AIHA, and CD4 lymphopenia noted in STK4 defect (pt." (PMID 33628209, 2020). "Furthermore, patients given combination therapy showed a higher degree of lymphopenia, affecting both naïve and memory CD4+ T cells." (PMID 31900171, 2020).
lymphopenia (continued). "The development of lymphopenia in severe case patients was mainly related to the significantly decreased absolute counts of T cells, including CD4+ and CD8+T cells, similar to the absolute counts of B cells and natural killer cells but not to the proportion of LYMs." (PMID 32484453, 2020). "CD4+ T lymphopenia was observed in 100% of the severe and critical cases." (PMID 33362779, 2020). "As such, lymphocyte evaluation, specially CD4, may be useful as predictor of gravity and outcome, in fact, patients with more severe clinical illness, or patients who died, had significantly more profound CD4+ lymphopenia." (PMID 32640747, 2020). "In addition, most patients in severe condition developed marked lymphopenia with significant reduction in lymphocytes, mainly CD4+ T cells, CD+8 T cells, regulatory T cells, NK cells, and B cells." (PMID 33233369, 2020). "Further characterization of the immune subsets suggests that the lymphopenia impacts CD4 and CD8 populations essential for antiviral immunity, and initial soluble factor results may be indicative of impaired antibody responses." (PMID 33219091, 2020). "Furthermore, lymphopenia with the suppression of B, helper (CD4+) and cytotoxic (CD8+) T cell function, is an indicator of a poor clinical outcome." (PMID 33384690, 2020). "In conclusion, our investigation addresses, for the first time, the importance of thymic function for the maintenance of the naïve CD4+ T-cell compartment in septic patients; we have identified decreased thymic output as a possible confounder for septic lymphopenia and immune suppression." (PMID 32825352, 2020). "This increase might be due to exposure to more selective suppressive chemotherapy such as fludarabine and the use of high-dose of steroids which depresses CD4 T-lymphocyte leading to a prolonged lymphopenia or T-cell dysfunction." (PMID 32183884, 2020). "Moreover, a state of moderate lymphopenia is also observed due to a decrease in the number of CD4 and CD8 T lymphocytes." (PMID 33233369, 2020). "While lymphopenia may drive CD4+ TN cell loss, we may be able to intervene with dendritic cell (DC) vaccination, checkpoint blockade, or metabolic interventions during post-ASCT lymphopenia to better support the recovering T cell population." (PMID 33013907, 2020). "In addition, patient #1 showed a profound T- and CD4-lymphopenia (190/μL absolute counts) and a low percentage of naïve CD4+ cells." (PMID 31947836, 2020). "In addition, all patients showed a relevant CD4-lymphopenia (all patients < 200/μL) with low levels of naïve CD4 cells (< 10% in all patients)." (PMID 31947836, 2020). "It has already been shown that treatment-induced lymphopenia is not a random process, and susceptibility to intensive chemotherapy differs between T cell subsets (i.e., CD4, CD8, and Tregs) and/or NK and B cells." (PMID 33204734, 2020). "CD4+ T-cell lymphopenia may blunt the adaptive immune response to SARS-CoV-2, and even further exacerbate hyperinflammation through impaired downregulation of inflammatory mediators." (PMID 33375371, 2020). "Overall, grade 3–4 lymphopenia was shown to occur in the majority of patients receiving standard-of-care treatment, with severe lymphopenia being an independent predictor of poor survival, and immune cell modulation was shown to be mostly restricted to CD4 T cells and B lymphocytes." (PMID 32117743, 2020). "In addition, patient #4 showed profound T- and CD4-lymphopenia (180/μL absolute counts) including a low percentage of naïve CD4+ cells (1%)." (PMID 31947836, 2020). "Several publications implied a role of rituximab in causing CD4 lymphopenia, although most patients treated with rituximab did not have serial CD4 measurements." (PMID 32915907, 2020). "We identified lymphopenia (<1000/mcl) as a risk-factor (OR 7.96), but we did not have CD4 lymphocyte counts for our non-HIV patients." (PMID 32915907, 2020).
lymphopenia (continued). "Nevertheless, it was reported that the number of CD4+ cells reached normal levels in blood one week after infections suggesting trafficking of CD4+ cells instead of inflow of de novo-generated cells after apoptosis-induced lymphopenia." (PMID 32481512, 2020). "Moreover, lymphopenia, with a decrease in CD4 + T-cells, which are often observed in cancer patients, compromises the anti-tumor response mediated by lymphocytes." (PMID 32631294, 2020). "Interestingly, these patients also exhibited CD4+ T cell lymphopenias, which in one case was already present prior to EBV infection." (PMID 32251475, 2020). "Among patients with persistent severe lymphopenia evaluation of CD4/CD8 ratio by flow cytometry and/or antimicrobial prophylaxis with trimethoprim/sulfamethoxazole and azithromycin could be considered with persistently low CD4 count." (PMID 33659205, 2020). "Indications for immune correction therapy may be progressive lymphopenia (below 900 cells/μL) and a decrease of CD4+ Th cells." (PMID 32722596, 2020). "Moreover, patient #3 also showed CD4-lymphopenia (100/μL absolute cell count) with low naïve CD4 cells." (PMID 31947836, 2020). "Because in our study the CD4+ T cell responses against lytic EBV peptides were similar in KTRs and in HCs, the specific loss of CD4+ T cell responses against latent EBV peptides cannot be fully explained by the persistent CD4+ T cell lymphopenia observed in our patients." (PMID 31639143, 2019). "In contrast, the absence of Vγ4+ and Vγ6+ γδ T cells was associated with splenic lymphopenia, and a pronounced loss of CD4+ but not of CD8+ αβ T cells." (PMID 31237933, 2019). "This may be due to the fact that 15%–82% of SLE patients have lymphopenia, as reduced CD4+ T cell proportions would result in reduced iSEXS scores." (PMID 31722210, 2019). "In summary, we provide evidence that the suppression of CD4+ T cell activation in response to lymphopenia is determined by a combination of both, clone-specific properties and environmental factors such as the commensal microflora, IL-6 and IFN-γR expression by DCs." (PMID 30792713, 2019). "Isolated CD8 lymphopenia with preserved CD4 counts can be seen with TAP1, TAP2, and ZAP70 defects." (PMID 31572360, 2019). "Additionally, LIP of lymphopenia-insensitive CD4+ T cells requires an intact microflora and is accompanied by the massive accumulation of IL-6 and dendritic cells (DCs)." (PMID 30792713, 2019). "Importantly, we found TREC copies to be higher than typical SCIDs in children with either CD4 or CD8 lymphopenia." (PMID 30778343, 2019). "Thus, sepsis-induced lymphopenia was, in fact, restricted to CD4 T cells in lymph nodes under our experimental conditions of CLP." (PMID 31323786, 2019). "ALPS-FAS has not been previously associated with CD4 lymphopenia and such finding in our index patient was unexpected and counterintuitive in a disorder of FAS-mediated apoptosis, which is usually associated with lymphocytosis and lymphoproliferation." (PMID 31191551, 2019). "Different immunotherapy treatments have been evaluated in HIV “immune non-responders” patients, but also in patients with virus-induced (HCV) chronic hepatitis, idiopathic CD4+ lymphopenia, and hematological malignancies treated with HSCT, or in chemotherapy-treated advanced cancer patients." (PMID 30922400, 2019). "Consequently, the adoptive transfer of polyclonal naive CD4+ T cells into lymphopenic mice leads to their activation and subsequent lymphopenia-induced proliferation (LIP)." (PMID 30792713, 2019). "Hence, the insensitivity of CD4+ T cells to lymphopenia relies on cell-intrinsic properties and a complex interplay between the commensal microflora, IL-6, IFN-γR+ DCs, and T cell-derived IFN-γ." (PMID 30792713, 2019).
lymphopenia (continued). "Hence, these observations indicate that Treg are lysed together with other CD4+ T-cells and—in response to treatment-induced lymphopenia—then either expand to preferentially acquire a memory phenotype and/or are converted from post-depletional Tcon." (PMID 31214176, 2019). "Moreover, lymphopenia with a decrease in CD4+T-cells, which are often found in patients with cancer, will compromise the antitumor response mediated by lymphocytes." (PMID 29570259, 2019). "Flow cytometric analysis of T-cell subpopulations confirmed CD4 lymphopenia (CD4 189 cells/μL), normal numbers of CD8 T cells (383 cells/μL), and an increased proportion and absolute number of CD3+TCRαβ+CD4−CD8− double negative T cells (DNT) (4.3%, 33 cells/μL)." (PMID 31191551, 2019). "HSCT corrected T-cell lymphopenia by expansion of CD4+ and CD8+ T-cells, and CD19+ cells." (PMID 31849966, 2019). "The most common immunodeficiency in non-HIV cryptococcal meningitis is idiopathic CD4+ lymphopenia, a disease caused by various alleles, which is seen in over 25% of cases." (PMID 30755511, 2019). "Moreover, malaria has several immunomodulating effects during acute infection including lymphopenia, decreased levels of CD4+ T cells, and a functional immunosuppression greater than can be attributed to the quantitative fall in CD4+ cells." (PMID 31294001, 2019). "Considering the possible lymphopenia that may occur in SLE patients, and that decreased total number of CD4+ T cells may cause calculated “normal” even “increase” in Tregs, some studies simultaneously provided data on the absolute numbers of Tregs." (PMID 30833946, 2019). "Arguing against a relevant role of CD4+ T cells, patients with MHC class II deficiency have a severe CD4 lymphopenia and do not develop EBV-driven LPDs and they have normal B cell counts." (PMID 29942301, 2018). "GS patients often display CD4+ T cell lymphopenia and an inverse ratio of CD4+/CD8+." (PMID 29850635, 2018). "The reconstitution pattern of Tregs after HSCT may differ from that of conventional CD4+ T cells and is influenced by the extent of CD4+ T cell lymphopenia as well as the incidence and severity of GvHD." (PMID 30093901, 2018). "Current studies suggest that CD4+ T-cell lymphocytopenia coupled with increases in IL-10-producing regulatory subsets specifically within the CNS may be most relevant." (PMID 29456537, 2018). "A perturbed immune surveillance due to CD4 lymphopenia has to be taken into account as an EBV independent mechanism that may promote lymphoma development." (PMID 30386345, 2018). "Human immunodeficiency virus (HIV) testing, serum protein electrophoresis, serum light chains and quantitative immunoglobulins were non-diagnostic and CD4 lymphopenia was attributed to acute infection." (PMID 29515938, 2018). "The only immunological feature common to all known etiologies is CD4+ lymphopenia." (PMID 29946305, 2018). "Transient lymphopenia has been reported previously in a clinical trial of a ChAd63-vectored Leishmania vaccine; however, in this study it was attributed to a predominant reduction in the frequency of CD4+ T cells." (PMID 30713538, 2018). "However, a persistent CD4 lymphopenia was seen in subsequent outpatient testing, which prompted a detailed workup for secondary causes of immunodeficiency." (PMID 29515938, 2018). "A similar cohort with CD4 lymphopenia is presented by patients with HIV infections." (PMID 30386345, 2018). "CD4+ lymphopenia and neutropenia can also be seen but are less pronounced." (PMID 29988375, 2018). "The TCR-transgenic TCR75 CD4 T cells undergoe only minimal lymphopenia-induced homeostatic proliferation, but would be expected to undergo robust antigen-specific expansion upon encounter of target H-2Kd allopeptide in transplanted recipients, with presumably, acquisition of TFH cell phenotype." (PMID 30728823, 2018).